PBX1 (PBX homeobox 1)
Diseases named in the same sentence as PBX1 in open-access papers (continued):
Sharing a sentence is not in itself a finding about the gene and the disease.
MRKH syndrome (3 papers, 2006 to 2021). "This association study successfully identified two susceptibility SNPs (WNT9B and PBX1) associated with MRKH syndrome risk, both separately and interactively." (PMID 26075712, 2015). "The dominant models of rs34072914 and rs2275558 in WNT9B and PBX1, respectively, were significantly associated with MRKH syndrome risk in the Chinese Han patients." (PMID 26075712, 2015). "We observed significant additive interaction between the variants rs34072914 in WNT9B and rs2275558 in PBX1, which were each separately associated with MRKH syndrome risk in this cohort." (PMID 26075712, 2015). "This study successfully identified two known SNPs (WNT9B and PBX1) that were separately and synergistically associated with MRKH syndrome and increased its risk in this case-control cohort." (PMID 26075712, 2015). "However, a subsequent study found a susceptibility SNP in PBX1 (rs2275558) associated with the MRKH syndrome." (PMID 34160006, 2021). "The dominant model (AG/AA) of PBX1 rs2275558 was found to be significantly associated with MRKH syndrome in this study, and made the genotype carriers 1.75 times higher risk of MRKH syndrome." (PMID 26075712, 2015). "Among these cofactors, PBX1 is of great interest in regards to malformations found in MRKH syndrome: it is required for skeletal development and patterning, kidney morphogenesis and especially, its gene inactivation leads to absence of Müllerian structures." (PMID 16556301, 2006). "Sequence analysis of coding regions of HOX candidate genes and of PBX1, a likely HOX cofactor during Müllerian duct differentiation and kidney morphogenesis, did not reveal any mutation in patients showing various forms of MRKH syndrome." (PMID 16556301, 2006). "Multifactor dimensionality reduction (MDR) analysis revealed novel dimensional epistatic four-gene effects (AMH, PBX1, WNT7A and WNT9B) in MRKH syndrome." (PMID 26075712, 2015). "The discovery of a four-gene epistatic effect (AMH, PBX1, WNT7A and WNT9B) in MRKH syndrome provides novel information for the elucidation of the genetic mechanism underlying the etiology of MRKH syndrome." (PMID 26075712, 2015). "The best four-way interaction model indicated by MDR analysis supported the following novel and bold assumption that the dimensional interactions of AMH, PBX1, WNT7A and WNT9B may play a role in the etiology of MRKH syndrome during MD development." (PMID 26075712, 2015). "Notably, we found a novel dimensional epistatic four-gene effect (AMH, PBX1, WNT7A and WNT9B) in MRKH syndrome, providing novel data to contribute to the elucidation of the genetic mechanisms underlying its multifactorial etiology." (PMID 26075712, 2015). "Numerous genes exhibiting a wide range of activity during MD development, such as PBX1, HOX family genes, WNT family genes and ant-Müllerian hormone (AMH), have been suggested as candidates for MRKH syndrome based on phenotypes that have been observed in mutant mice." (PMID 26075712, 2015).
myeloma (3 papers, 2024 to 2025). "PHF19 expression in myeloma cell lines is greatly reduced by PBX1 silencing, although PBX1 amplification on 1q greatly enhances PHF19 levels." (PMID 41226583, 2025). "For instance, in myeloma cells displaying amplification of chromosome 1, ectopic expression of PBX1, situated at 1q23.3, has been documented." (PMID 41226583, 2025). "When myeloma cell lines overexpressed PBX1, we saw the opposite effect of the knockdown of PBX1 on PHF19 expression." (PMID 38755140, 2024). "Additionally, drugs that interfere with the PBX1-FOXM1 axis or PBX1 small-molecule inhibitors have been proposed as potential treatment alternatives for chr1q-amp myeloma." (PMID 41226583, 2025). "Thus, PBX1 and PHF19 may identify high-risk myeloma subtypes, necessitating more intensive treatment." (PMID 41226583, 2025). "The overexpression of PBX1 induces FOXM1 upregulation, thereby influencing the biologic behavior of the disease and the proliferation of myeloma cells." (PMID 41226583, 2025). "Knockdown of PBX1 attenuates the effect of NEAT1-silenced exosomes on NK cells and multiple myeloma cells." (PMID 39346921, 2024). "Therefore, Exosomal lncRNA NEAT1 is up-regulated in multiple myeloma, and NEAT1 represses PBX1 by recruiting EZH2." (PMID 39346921, 2024).
Autoimmunity (2 papers, 2022 to 2024). The occurrence of an immune reaction against the organism's own cells or tissues. "A disruption of the Pbx1/NFIL3 axis is therefore a potential mechanism by which Pbx1-d may alter the Treg/Tfh cell balance in favor of autoimmunity." (PMID 35693798, 2022). "The homeostasis of the immune system also relies on PBX1 since, together with PREP1, PBX1 mediates the transcriptional activation of IL10 in phagocytes stimulated by apoptotic cells, thus favoring suppression of autoimmunity." (PMID 38404687, 2024).
bone tumors (2 papers, 2011 to 2024). "An EWSR1/POU5F1, EWSR1/PBX1 or EWSR1/ZNF444 fusion gene, or a rearrangement of the EWSR1 gene with unknown fusion partner, was detected in close to half of the soft tissue lesions, and in four out of five bone tumors." (PMID 22588017, 2011).
breast tumors (2 papers, 2011 to 2015). "PBX1 regulates a subset of EGF-ERα genes highly expressed in aggressive breast tumours." (PMID 26215677, 2015). "Indeed, while FoxA1 expression in ERα-positive primary breast tumors does not discriminate their metastasis-free outcome, elevated PBX1 expression has significant prognostic potential towards metastasis." (PMID 22125492, 2011).
chronic myeloid leukemia (2 papers, 2023 to 2025). "PBX1 appears to be a significant factor in chronic myeloid leukemia (CML) as it promotes tumor cell proliferation through its interaction with RNF6, a direct target of PBX1." (PMID 41226583, 2025).
colon cancer (2 papers, 2012 to 2021). "In Pbx1-deficient dopaminergic neurons, the high affinity netrin-1 receptor, deleted in colon cancer (DCC), is down-regulated." (PMID 22748019, 2012). "Furthermore, our analysis of Pbx1 mutant mice demonstrates a role of Pbx1 in axon guidance through the regulation of the netrin-1 receptor, deleted in colon cancer (DCC)." (PMID 22748019, 2012).
congenital heart disease (2 papers, 2021 to 2022). A heart disease that is present at birth. "PBX1 could be a candidate gene for fetal growth restriction, renal hypoplasia and congenital heart disease." (PMID 34630509, 2021).
embryonal carcinoma (2 papers, 2011 to 2022). A non-seminomatous malignant germ cell tumor characterized by the presence of large germ cells with abundant cytoplasm resembling epithelial cells, geographic necrosis, high mitotic activity, and pseudoglandular and pseudopapillary structures formation. "Previous studies have shown that all-trans retinoic acid induced the expression of PBX1 at mRNA level in P19 embryonic carcinoma cells, whereas the PBX3 mRNA level remained unchanged." (PMID 21548940, 2011). "The expression of PBX1, PBX2, and PBX3 was upregulated during endodermal and neuronal differentiation of embryonal carcinoma P19 cells in a RAR‐dependent subtype‐unspecific manner following RA treatment." (PMID 35068042, 2022).
endometrial cancer (2 papers, 2019 to 2021). Primary or metastatic malignant neoplasm involving the endometrium (mucous membrane that lines the endometrial cavity). "Our transcriptome assay uncovered that Ephrin-B2 (EFNB2) and Pre-B cell leukaemia homobox-1 (PBX1) were the two recurrently downregulated DEGs in sfTSLP-expressing ovarian and endometrial cancer cells." (PMID 33652749, 2021). "We further investigated the impact of sfTSLP overexpression on transcriptome by RNA-sequencing and found that EFNB2 and PBX1 were downregulated in ovarian and endometrial cancer cells, suggesting their role in sfTSLP-mediated tumour growth." (PMID 33652749, 2021).
gastric tumor (2 papers, 2015 to 2023). "Neck cell differentiation-related group C contained TFs such as Hes1, Pbx1, and Spdef, whereas isthmus progenitor cell-related group D again contained gastric tumor-related TFs such as Dnmt1 and Foxm1." (PMID 37386010, 2023). "Instead, Pbx1 seems stably expressed in both gastric tumor and normal tissues." (PMID 26536658, 2015).
Hypoinsulinemia (2 papers, 2008 to 2018). A decreased concentration of insulin in the blood. "Pbx1 null mice exhibit severe defects in pancreatic exocrine and endocrine cell differentiation and die at E15-16, while Pbx1+/- mice have pancreatic islet malformation, impaired glucose tolerance and hypoinsulinemia." (PMID 18312624, 2008).
liver fibrosis (2 papers, 2024 to 2025). "A recent study reported that PBX1 promotes HF through IL-17 signaling transduction in hepatic stellate cells, and the development of liver fibrosis would be alleviated when blocking the IL-17 signaling axis." (PMID 40421012, 2025). "Five patients had liver diseases (polycystic liver disease, liver fibrosis, liver cirrhosis, or chronic hepatitis B) with an average of 97 small somatic variants, including nonsilent variants in ARID1A, CSMD3, and KEAP1 and one copy gain of PBX1." (PMID 38877653, 2024).
oesophageal cancer (2 papers, 2022 to 2023). "PBX1 acted as pioneer transcription factor to mediate the binding of FoxC1 to ZEB2 promoter in oesophageal cancer cells." (PMID 35068042, 2022).
ovarian tumor (2 papers, 2011 to 2020). "Previous work by Crijns and colleagues reported increased PBX immunohistochemical staining in both cytoplasm and nuclei of ovarian tumor cells using an anti-PBX1/2/3/4 antibody, which does not differentiate between the different PBX members." (PMID 21548940, 2011).
psoriasis (2 papers, 2024 to 2025). An autoimmune condition characterized by red, well-delineated plaques with silvery scales that are usually on the extensor surfaces and scalp. "Mechanistically, our results showed that Snora73 acted as a sponge for miR-3074-5p and PBX1 is a direct target of miR-3074-5p in psoriasis cells." (PMID 38240925, 2024). "We also found that the PBX1 level was passively connected to the miR-3074-5p level among psoriasis tissues." (PMID 38240925, 2024). "Collectively, these findings reveal a crucial role of Snora73 in progression of psoriasis through miR-3074-5p/PBX1 signaling pathway and suggest a potential therapeutic strategy." (PMID 38240925, 2024). "Elevated PBX-1 expression can promote keratinocyte activity, leading to inflammation and thickening of the skin, resulting in the plaques and scales characteristically observed in psoriasis patients." (PMID 40161116, 2025). "By targeting the binding of Snora73 with miR-3074-5p, excessive production of PBX-1 may be reduced, curbing the erratic keratinocyte proliferation notable in psoriasis." (PMID 40161116, 2025). "Furthermore, miR-3074-5p suppressed psoriasis cell proliferation and migration, while PBX1 promoted cell proliferation and migration in psoriasis." (PMID 38240925, 2024). "Then, the expression of top 5 potential candidate genes (PBX1, CYB5R4, SAR1A, CXCR5, MFSD6) of miR-3074-5p was detected in normal and psoriasis tissues by qPCR; our result revealed that PBX1 was the most upregulated genes in psoriasis tissues compare to normal ones." (PMID 38240925, 2024). "Importantly, we found that Snora73 acted as a sponge for miR-3074-5p and PBX1 is a direct target of miR-3074-5p in psoriasis cells." (PMID 38240925, 2024). "These suggest that miR-3074-5p inhibits psoriasis progression through inhibiting PBX1." (PMID 38240925, 2024). "Furthermore, by directly addressing post-transcriptional dysregulation of PBX1 expression, patients who experience chronic or treatment-resistant psoriasis could potentially experience a reduction in both the severity and frequency of psoriatic episodes." (PMID 40161116, 2025). "However, the molecular mechanisms of PBX1 in psoriasis remains elusive." (PMID 38240925, 2024). "Also, we validated PBX1 was a miR-3074-5p target, which maybe a promising therapeutic target for psoriasis." (PMID 38240925, 2024). "Snora73 regulates cell proliferation by interacting with miR-3074-5p and pre-B-cell leukemia homeobox 1 (PBX1), promoting abnormal cell turnover in psoriasis." (PMID 40161116, 2025). "The Snora 73-mediated regulation of PBX-1 expression introduces a pathway that may explain how non-coding RNA activity contributes to the dysregulation of inflammation and keratinocyte proliferation in the progression of psoriasis." (PMID 40161116, 2025).
renal agenesis (2 papers, 2021 to 2023). Renal agenesis (RA) is a form of renal tract malformation characterized by the complete absence of development of one or both kidneys (unilateral RA or bilateral RA respectively), accompanied by absent ureter(s). "PBX1 has been identified as a monogenic cause of CAKUT in mammals, with Le Tanno via microarray analysis previously reporting pathogenic variation in microdeletion-related genes as a cause of renal agenesis, with PBX1 as the smallest common region." (PMID 37006624, 2023). "Renal agenesis, hyperechogenicity, pelvicalyceal dilation, bilateral nephroureters, ectopic kidneys, horseshoe-shaped kidneys, bilateral vesicoureteral reflux, and small urethral valves are common PBX1 mutant renal phenotypes, though renal agenesis is rarer." (PMID 37006624, 2023).
renal hypoplasia (2 papers, 2021 to 2025). Renal hypoplasia is a developmental anomaly in which one or both kidneys (unilateral or bilateral renal hypoplasia, respectively) have a deficit in the number of nephrons and may be small. "Although information on the presence of renal hypoplasia at birth was unavailable, the renal phenotype in our patient remained largely subclinical until the onset of renal function decline and the development of proteinuria, despite the presence of a truncating PBX1 variant." (PMID 41255624, 2025).
T-cell ALL (2 papers, 2020 to 2025). "The immunophenotypic distribution according to fusion gene status followed expected patterns, with TEL::AML1, BCR::ABL, E2A::PBX1 and MLL::AF4 fusions exclusively associated with B-cell ALL and SIL::TAL1 fusion predominantly found in T-cell ALL." (PMID 41234729, 2025).
alcoholism (1 paper, 2021). "In contrast, the group 1 peaks, where HOXB1 and PBX1 display co-occupancy, associate with genes required in cancer and alcoholism, while the group 2 regions with co-binding of HOXB1 and REST associate with genes required in neurogenesis, neuronal processes, and behavior." (PMID 33546292, 2021).
asplenia (1 paper, 2020). "Using trio exome sequencing, we identified a PBX1 p.(Arg107Trp) mutation in a deceased one-day-old neonate presenting with CAKUT, asplenia, and severe bilateral diaphragmatic thinning and eventration." (PMID 32141698, 2020).
autism (1 paper, 2025). Persistent deficits in social interaction and communication and interaction as well as a markedly restricted repertoire of activity and interest as well as repetitive patterns of behavior. "Additionally, two de novo loss-of-function variants and two rare, potentially damaging missense variants in the PBX1 gene were reported in ASD probands from the Autism Sequencing Consortium and the SPARK cohort." (PMID 41231825, 2025).
autism spectrum disorder (1 paper, 2023). A spectrum of developmental disorders that includes autism, and Asperger syndrome. "The enrichment of PBX1, which targets the genes Cga and Prl, can be related to findings that this transcription factor was associated with autism spectrum disorder in a transcriptome study of adult cortical tissue in humans." (PMID 37851674, 2023).
autoimmune disease (1 paper, 2025). A disorder resulting from loss of function or tissue destruction of an organ or multiple organs, arising from humoral or cellular immune responses of the individual to their own tissue constituents. "In recent years, as a transcription factor, PBX1 has been abundantly demonstrated to play a key role in tumorigenesis as well as in the pathogenesis of autoimmune diseases (e.g. SLE), and it is increasingly likely to be a therapeutic target." (PMID 40299657, 2025).
benign ganglioneuromas (1 paper, 2018). "Finally, the authors demonstrated that in primary NBL tumor tissue, PBX1 expression correlated with the histological NBL subtype, with the highest PBX1 expression in benign ganglioneuromas and the lowest expression in high-risk NBL." (PMID 30384831, 2018).
cervical neoplasms (1 paper, 2025). "Additionally, miR-4428 is implicated in colonic and cervical neoplasms through regulatory interactions affecting BCL2L11 and PBX1 expression, respectively." (PMID 40282289, 2025).
chronic kidney disease (1 paper, 2025). Impairment of the renal function secondary to chronic kidney damage persisting for three or more months. "Here, we present a 28-year-old male diagnosed with a rare PBX1 nonsense variant identified during the evaluation of early-onset chronic kidney disease." (PMID 41255624, 2025). "This case provides histopathologic insight into the renal features associated with a PBX1 variant and highlights the importance of genetic evaluation in adults presenting with early-onset chronic kidney disease (CKD) of undetermined cause." (PMID 41255624, 2025).
cleft lip (1 paper, 2015). Congenital defect in the upper lip where the maxillary prominence fails to merge with the merged medial nasal prominences. "The biological interaction between WNT9B and PBX1 has been studied in cleft lip and/or palate resulting from abnormal morphogenesis of the face." (PMID 26075712, 2015).
colorectal tumors (1 paper, 2023). "To investigate the function of PBX1 in colorectal tumors, we chose two cell lines, LoVo and HCT116, which had low PBX1expression levels in CRC cell lines, to overexpress the PBX1 protein." (PMID 36739270, 2023).
congenital neutropenia (1 paper, 2022). "In the myeloid lineage, the aberrant expression of PBX1 has been associated with severe congenital neutropenia." (PMID 35328612, 2022).
cystinuria (1 paper, 2019). Cystinuria is a renal tubular amino acid transport disorder characterized by recurrent formation of kidneys cystine stones. "There is a 3‐fold increase in the risk of the development of cystinuria among individuals with this particular SNP in the PBX1 gene." (PMID 30450686, 2019). "Here, we found an association between a SNP in Pre‐B‐cell leukaemia transcription factor 1 (PBX1) gene and the risk of development of cystinuria." (PMID 30450686, 2019). "The risk of development of cystinuria increased three‐fold in association with the SNP in PBX1 gene, and the presence of this SNP could change the expression of PBX1, affecting renal reabsorption of cystine and other amino acids, possibly predisposing to cystinuria development." (PMID 30450686, 2019). "Pre‐B‐cell leukaemia transcription factor 1 (PBX1) was overexpressed 3.3‐fold in patients with cystinuria." (PMID 30450686, 2019). "For this reason, we performed qRT‐PCR for to evaluate PBX1 gene expression in patients with cystinuria, and curiously, we found overexpression of PBX1 in patients with one or no mutated allele and underexpression of PBX1 in patients with two mutated alleles." (PMID 30450686, 2019).
diaphragmatic hernia (1 paper, 2022). A congenital or acquired weakness or opening in the diaphragm which allows abdominal contents to protrude into the chest cavity; congenital diaphragmatic hernias are caused when the embryonic diaphragm fails to fuse. "Patients with pathogenic PBX1 variants/microdeletions showed pleiotropic developmental defects, including external ear anomalies, abnormal branchial arch derivatives, heart malformations, diaphragmatic hernia, renal hypoplasia and ambiguous genitalia." (PMID 36544198, 2022).
diffuse large B-cell lymphoma (1 paper, 2025). "Modifications of the PBX1 gene have been verified in non-Hodgkin B-cell lymphomas, particularly Burkitt lymphoma and diffuse large B-cell lymphoma (DLBCL)." (PMID 41226583, 2025).